VCL (vinculin)
Diseases named in the same sentence as VCL in open-access papers (continued):
Sharing a sentence is not in itself a finding about the gene and the disease.
tumor (continued). "To understand the forces on focal adhesions of tumor cells interacting with osteocytes, we conducted FRET analysis using a vinculin tension sensor transfected into the tumor cells." (PMID 30948840, 2019). "In this study, we evaluated tumor-osteocyte interactions using the vinculin tension sensor and real-time live cell imaging." (PMID 30948840, 2019). "Vinculin, an F-actin binding protein, has been suggested as a tumor suppressor by reducing tumor metastasis through decrease cell motility." (PMID 29854771, 2018). "Beyond tumor growth, we also detected several DEGs enriched in metastasis, including vinculin (VCL) and Tumor necrosis factor (TNF) receptor superfamily member 12A (TNFRSF12A)." (PMID 30301189, 2018). "Vinculin supports anchorage-dependent cell growth decreasing cell motility and has been suggested to function as a tumor suppressor." (PMID 29854771, 2018). "The results showed that tumours formed by vinculin knockdown cells were more metastatic compared with those of the control cells, and, after 4 weeks, lymph node metastasis was observed in the mice injected with vinculin knockdown cells." (PMID 28266545, 2017). "Tumours from GM6001-treated cells were less metastatic than those from control cells, and tumours from GM6001-treated Cas9-vinculin cells and control cells had similar levels of metastasis." (PMID 28266545, 2017). "Similar to other HNSCC cell lines from primary tumor, liprin-α1 was found either around the cortactin-containing core outside of vinculin or at the lamellipodia at the vicinity of vinculin positive small focal adhesions." (PMID 27075696, 2016). "Conversely, p23−/− MEFs present a vinculin impairment, strongly suggesting involvement of p23 in driving tumour cells towards high invasion profiles via modulating some EMT‐dependent cellular changes and interactions within cytoskeleton components." (PMID 25241147, 2015). "Further supporting this possible role of p23, ectopic expression of the chaperone enhances vinculin expression, which is implicated in the epithelial to mesenchymal transition (EMT) and tumour spreading." (PMID 25241147, 2015). "Based on these findings, we propose a model of metastasis control in which reduced expression of NME2 in tumor cells perturbs focal adhesion signaling by enhancing expression of vinculin." (PMID 25249619, 2014). "Using this replication population of samples, they were able to detect seven genes with tumour-specific splice variants (ACTN1, CALD1, COL6A3, LRRFIP2, PIK4CB, TPM1 and VCL)." (PMID 24179441, 2013). "This is in agreement with smaller patches of paxillin and vinculin observed in metastatic-derived cell lines (SW620) compared to their primary tumor-derived cell lines (SW480)." (PMID 24260200, 2013). "Cells treated with recombinant Wnt5a demonstrated a decrease in both ALCAM and vinculin, supporting the hypothesis that the interaction of these two proteins is affected by Wnt5a in the tumor microenvironment." (PMID 41301074, 2025). "Moreover, in vivo, intratumoral delivery of miR-633b suppressed VCL expression and inhibited tumor growth by limiting angiogenesis." (PMID 41148856, 2025). "Together, these findings suggest that exosomal VCL may be actively regulated during metastasis and play a role in reprogramming tumor cell communication, thereby facilitating adaptation to the brain microenvironment." (PMID 40563579, 2025). "Moreover, within an MTT-based cell viability assay framework, VCL overexpression emerged as an enhancer of the anti-tumor potential inherent to LIV-treated MSC CM." (PMID 38389836, 2024). "The enhanced tumor suppressive effect by VCL overexpression was also observed using hMSCs." (PMID 38389836, 2024). "The up-regulated expression of Mmps genes and down-regulated expression of focal adhesion genes including Talin, paxillin, vinculin, and Src, in tumor hybrid cells, indicated a greater ability of hybrid cells to detach from the tumor tissue and form distant metastasis." (PMID 37138326, 2023).
tumor (continued). "Not surprisingly, the low expression of FAK, paxillin, vinculin, and cortactin predicts good survival outcomes, considering that several studies report an association between their overexpression and tumor aggressiveness." (PMID 37686651, 2023). "In squamous cell carcinomas, the interaction of N-cadherin, located on the surface of CAFs, with tumor cell E-cadherin promotes tumor invasion through the activation of the β-catenin–vinculin signaling pathway and, as a consequence, actin remodeling in both types of migrating cells." (PMID 38003931, 2023). "Indeed, platinum NP treatment in HUVECs led to dysfunctional intracellular junctions whilst decreasing the expression of VE-cadherin, epithelial protein lost in neoplasm and vinculin, all of which are important mediatorsof cellular junctions." (PMID 37593220, 2023). "While searching for the core genes of tumor-infiltrating NK cells through WGCNA, we found that VCL may be an important target that causes high expression of NK cells." (PMID 33535187, 2021). "It proved that VCL can promote the proliferation of tumor cells." (PMID 33535187, 2021). "Vinculin influences metastasis and prognosis in several tumours." (PMID 34445479, 2021). "Therefore, we conclude that miR-663b, as a carcinogen, can be delivered into target cells through exosomes to downregulate VCL expression, thereby promoting tumor growth and angiogenesis in-vivo." (PMID 34923985, 2021). "Vinculin may act as a metastasis inhibitor by decreasing cell motility and tumour inhibitor by assisting anchorage-dependent cell growth." (PMID 33053689, 2020). "By measuring focal adhesion forces with a vinculin tension sensor and analyzing migratory behavior with real-time live cell imaging, this study revealed that metastatic tumor cells are attracted to osteocytes, and this attraction is reversed by applying mechanical stimulation to osteocytes." (PMID 30948840, 2019). "Tumor cells were transfected with the vinculin tension sensors." (PMID 30948840, 2019). "Targeting integrins with monoclonal antibodies or pharmaceutical agents, such as vinculin activators, may prove of importance for the treatment of such tumours." (PMID 22333601, 2012). "At a molecular level there is evidence for two pathways indicating that vinculin may act as a tumour suppressor by inhibiting ERK (Extracellular signal-Regulated Kinase), a protein which has a key role in the regulation of cell proliferation." (PMID 20655620, 2011). "In addition, talin and vinculin have also been investigated as potential novel tumour biomarkers." (PMID 40045379, 2025). "An increase in the betweenness centrality of a node/gene in tumor samples indicates that the gene lies on shorter paths connecting other genes, suggesting its role as a bridge in tumor-related PPIs, for instance, VCL, FLNA, TNS1, GATA3, and ITGB3, which may act as key connectors in tumor samples." (PMID 40626556, 2025). "CBX may thus affect tumor cell invasion and adhesion via ZO-1 and vinculin." (PMID 37232747, 2023). "However, the mechanism by which CD147 regulates vinculin-FA should be tested in tumor cells." (PMID 25033086, 2014). "Specifically, NeoA treatment led to a delocalization of the focal adhesion scaffolding proteins paxillin and vinculin as well as a decrease in the phosphorylated form of focal adhesion kinase from characteristic longitudinal streaks at the cell-substratum interface in MDA-MB-231 tumor cells." (PMID 20520768, 2010). "Notably, tumor-specific splicing patterns of Alpha-actinin 1, caldesmon and Vinculin, key cytoskeleton components, were found in all three organs suggesting that they may represent general cancer related splicing events." (PMID 19516963, 2008). "Analysis initiated by fusions in the COSMIC-enriched cluster highlighted several putative or less appreciated oncogenic fusions, including CCAT1::CASC8 and VCL::ADK, based on their feature similarity to other well-known tumor-enriched fusions." (PMID 37323575, 2023).
tumor (continued). "NUMB, VCL, MAP3K7 and EXOC1 exon skipping events are examples of known splicing events that can be also observed in tumor tissue." (PMID 36304260, 2022). "Through in vivo experiments, we have determined that VCL can affect EMT and tumor immunity by regulating the expression of EPCAM." (PMID 33535187, 2021). "Using qRT-PCR, we also verified that the gene AS events SORBS2 were downregulated in tumor tissue, and gene AS events EPB41L2, CELF2, TMEM130, and VCL were upregulated in tumor tissue." (PMID 34692669, 2021). "Intravenous delivery of CTNNA1 siRNA with CA nanoparticles significantly reduced tumor volume in the initial phase of the study, while siRNAs targeting CTNNB1, TLN1, VCL, PXN, and ACTN1 genes significantly decreased the tumor burden at all time points." (PMID 31269666, 2019). "All antigens, and particularly EZR, VCL, VIM, PDC6I, hnRNPL and ANXA2 induced a specific antibody response in KC and KPC already at 1 to 3 months of age, when the tumor stage was limited to early PanIN." (PMID 24010981, 2013). "While primary tumor EV promote localized ATP synthesis, and thus, faster migration, the EV from metastasizing LAM cells promote the formation of IAC through the delivery of EV pool of IAC building blocks, including vinculin, paxillin and ILK1." (PMID 40166013, 2025). "Immunohistochemistry reveals tumor cell positivity for CD30, CD68, CD163, ALK1, ALK (D5F3), and EMA; Genetic testing shows ALK gene rearrangement in tumor cells but with different ALK fusion partners, mainly SQSTM1 (52%) and VCL (30%)." (PMID 38706599, 2024). "VCL was moderately positive in normal renal tissues according to HOA002131 staining (both glomerular and tubular cells were moderately positive) but weakly positive in tumor tissues." (PMID 37056387, 2023). "But through which complex regulatory mechanisms does vinculin affects MET, activates NK cell toxicity and causes tumor cell immune escape, and through in vivo experiments, we confirmed that VCL can affect EMT and tumor immunity by regulating the expression of EPCAM." (PMID 33535187, 2021). "Components of cellular focal adhesions such as vinculin, talin and paxillin interact with this kinase and are involved as parts of the focal adhesion complexes in the cell-ECM binding through integrins which can also be shown in spheroids used as tumor model." (PMID 34360970, 2021). "VCL can affect EMT and tumor immunity by regulating EPCAM gene expression." (PMID 33535187, 2021). "The expression of VCL was then measured by IHC, and the results showed that VCL increased in the Exo-miR-663b inh group and decreased in the Exo-miR-663b up group and had a negative relationship with tumor blood vessel density." (PMID 34923985, 2021). "A subgroup of the tumour-specific splicing variations (ACTN1, CALD1, and VCL) was observed in all three organs and may indicate general cancer-related splicing events." (PMID 24179441, 2013). "SMAR1 also inhibited the expression of Fibronectin, Vinculin and JAM2 that are involved in promoting cell-extracellular matrix adhesion, cell spreading and migration, suggesting that SMAR1 might prevent tumor cell metastases through negative regulation of these proteins." (PMID 17668048, 2007).
infection (33 papers, 2008 to 2025). The state of being infected such as from the introduction of a foreign agent such as serum, vaccine, antigenic substance or organism. "We used chemical cross-linking to identify induced interacting partners of TLR2 that contribute to bacterial immune escape, and found that infection induces TLR2 association with vinculin (VCL)." (PMID 37023213, 2023). "The determination of vinculin RFI/cell and counts of vinculin-positive FAs/cell over the time course of infection demonstrated that the loss of vinculin-positive FAs began in the sixth hour of infection." (PMID 36355522, 2022). "Moreover, these disruptions correlated with impaired wound healing of adenocarcinoma gastric epithelial cells (AGS), indicating that reduced phosphorylation of vinculin is a significant mechanism underlying the tissue damage caused during infection." (PMID 33572997, 2021). "Consistent with actin, the subcellular localization of cortactin and vinculin was also affected by infection." (PMID 41341493, 2025). "Contrasting to cortactin and similar to actin, vinculin expression remained unchanged at all time points and under all infection conditions." (PMID 41341493, 2025). "In our study we also found that the vinculin was cleaved during the infection into a 95 kDa fragment." (PMID 39376663, 2024). "In contrast, infection of A549 cells with CRAdFAST led to a ~10-fold reduction in vinculin and tubulin within the cells beginning at 48 hpi." (PMID 39596515, 2024). "Unexpectedly, we found the vinculin (124 kDa) was cleaved during the infection into a 95 kDa fragment." (PMID 39376663, 2024). "Another protein, Sca4, which with the cell adhesion protein vinculin enables the passage of the cell membrane, was expressed during infection." (PMID 37085774, 2023). "Immunoblotting using cytoplasmic lysates was carried out for HIV protease (HIVPR) activity, and vinculin (loading control) as indicated 24 hr post-infection." (PMID 37417868, 2023). "We then considered the changes to the cell surface, F-actin cytoskeleton, and vinculin-positive FAs over the time course of infection in cell monolayers colonized with L. gasseri ATCC 9857 or KS 120.1 before infection with Tv G3." (PMID 36355522, 2022). "Reduced phosphorylation at these residues during infection was observed to impair vinculin’s interaction with the p34Arc subunit of the Arp2/3 complex, which caused reduced lamellipodia formation." (PMID 33572997, 2021). "Moesin, vinculin, and actin cytoskeletons are host cell proteins which are disrupted during an infection via a diverse set of viral pathogens." (PMID 34696472, 2021). "First, we wanted to establish the role of vinculin in blebbistatin resistance of FAs in the context of infection." (PMID 32843479, 2020). "Immunofluorescence staining further showed that vinculin content was increased during E. coli O157:H7 infection, while integrin β1 KO impaired the accumulation of vinculin in response to infection." (PMID 30700983, 2018). "Unsurprisingly, a number of bacterial pathogens have been shown to employ vinculin to facilitate infection of host cells and dissemination within tissues." (PMID 26649283, 2015). "During invasion Shigella species modulates host vinculin expression to promote infection, making its down-regulation potentially important in CLas invasion processes." (PMID 26091106, 2015). "Overall, the highly localized recruitment of vinculin to the sites of entry, and the requirement for efficient invasion suggest that vinculin has an essential role in the infection of cultured cells by C. caviae GPIC." (PMID 26649283, 2015). "Vinculin was observed to be strongly concentrated around EBs as early as 10 min post-infection (p.i.)." (PMID 26649283, 2015). "Specifically, the concentration of profilin 1, α actinin, vinculin, and filamin A were found to be significantly altered by infection." (PMID 21507248, 2011).
infection (continued). "Importantly, Akt phosphorylation was enhanced in shVCL cells at baseline, prior to infection with P. gingivalis, suggesting that VCL regulates PI3K in the steady-state." (PMID 37023213, 2023). "Additionally, in IBS, it is assumed that infection with C. jejuni can trigger autoantibody formation, e.g., against vinculin, with direct effects on the intestine such as diarrhea due to destabilized TJs, as shown in a PI-IBS rat model." (PMID 36979384, 2023). "To validate the inducible interaction of TLR2 with VCL in response to infection with P. gingivalis, we next adapted a split-ubiquitin two-hybrid system originally designed to study inducible interactions between membrane proteins (Mammalian Membrane Two-Hybrid system, MaMTH)." (PMID 37023213, 2023). "We used this method to assay the solubility of several proteins during infection and found vinculin, a large cytoskeletal protein, to be soluble, histone H3 to be insoluble, and protein VII in both soluble and insoluble fractions, consistent with previous findings." (PMID 37703278, 2023). "The Gram-negative spiral bacterium Helicobacter pylori, the causative agent of peptic ulcer disease and a significant risk factor for gastric cancer, relies upon the dephosphorylation of vinculin to reduce FA numbers and lamellipodia formation during infection." (PMID 33572997, 2021). "Immunoprecipitation of GFP-IpaA revealed interaction with vinculin as early as 5 m post-infection." (PMID 33572997, 2021). "Additionally, vinculin was found to be recruited to sites of C. caviae entry while infection efficiency was reduced in vinculin KO cells, revealing that vinculin plays a role during invasion of C. caviae." (PMID 30629647, 2019). "Vinculin is exploited by a number of microbial pathogens as a means to productive infection." (PMID 26649283, 2015). "In contrast to the control, vinculin knockdown reduced infection by S. aureus in mouse lungs." (PMID 24466349, 2014). "Finally, vinculin and Rab5 knockdown reduced infection of S. aureus, phosphorylation of MAPKs and IL-6 expression in murine lungs." (PMID 24466349, 2014). "Our data showed that vinculin and Rab5 participated in infection of S. aureus in the mouse lung." (PMID 24466349, 2014). "After 24–36 h of infection, cells were fixed and stained for α−actinin and vinculin separately." (PMID 20635003, 2010). "For example, while infection with CRAd does not significantly alter the levels of vinculin and tubulin within the cells over a 72-h time course, infection with CRAdFAST caused a significant decline in the quantity of these proteins in the cell beginning at 48 hpi." (PMID 39596515, 2024). "Infection of monocyte-derived macrophages with HIV led to the upregulation of VCL, and, as a consequence, VCL negatively affected the propagation of the virus." (PMID 35696338, 2022). "In this study, infection with CagA+H. pylori led to a decrease in cortactin levels, but not vinculin, in BxPC-3 cells." (PMID 41341493, 2025). "However, the phosphorylation levels of vimentin, vinculin, paxillin, and LIM domain kinase 1 were upregulated at 6 h and 36 h after infection." (PMID 38759153, 2024). "In contrast, infection of the vcl−/− MEFs failed to inhibit blebbistatin-induced disassembly of focal adhesions, highlighting the crucial role of the host protein vinculin in FA stability." (PMID 32843479, 2020). "We identified an infection-dependent change to host cells (FA stability, FA reorganization, and restricted cell motility), a type III effector (TarP) responsible, the relevant target (FAs) of the effector, and an initial mechanism (vinculin dependence)." (PMID 32843479, 2020). "Vinculin is a key player in the regulation of FA dynamics 42 and cell:cell junctions 43, and the capacity of TarP VBS1 to uncouple vinculin‐mediated cytoskeletal connections during infection is therefore likely to have significant biological implications." (PMID 29710402, 2018).